WDR4 (WDR4 tRNA N7-guanosine methyltransferase non-catalytic subunit)
Diseases named in the same sentence as WDR4 in open-access papers (continued):
Sharing a sentence is not in itself a finding about the gene and the disease.
primordial dwarfism (16 papers, 2015 to 2025). "Homozygous missense mutation of WDR4 is found to cause microcephalic primordial dwarfism, manifested as severe growth retardation and brain abnormalities." (PMID 39255038, 2024). "WDR4 functions as a scaffold for METTL1 and tRNA binding, and WDR4-R170L homozygous mutation causes microcephalic primordial dwarfism." (PMID 39255038, 2024). "WDR4 R170L mutation was discovered from microcephalic primordial dwarfism patients showing an impairment of tRNA m7G methylation." (PMID 37821451, 2023). "Various WDR4 mutations were identified in patients with neurodevelopmental disorders, including primordial dwarfism and Galloway-Mowat syndrome." (PMID 36681682, 2023). "Our study identifies Wdr4 as a previously unappreciated participant in cerebellar development and locomotion, providing potential insights into treatment strategies for diseases with WDR4 mutations, such as primordial dwarfism and Galloway-Mowat syndrome." (PMID 36681682, 2023). "In humans, for example, a mutation in the methyltransferase complex WDR4 has been associated with primordial dwarfism, a condition marked by facial dysmorphism, brain malformation, and severe encephalopathy with convulsions." (PMID 35614925, 2022). "Studies show that primordial dwarfism patients with the WDR4–R170L missense mutation have defects in m7G levels in tRNA37." (PMID 34285249, 2021). "WDR4 gene with a missense mutation was reported to be related to primordial dwarfism through m7G46 methylation, which impaired transfer (t)RNAs." (PMID 34442404, 2021). "Very recently, mutations in WDR4, initially described to cause a distinct form of microcephalic primordial dwarfism and brain malformations, have been identified in individuals with GAMOS14." (PMID 31481669, 2019). "In a new study published in Genome Biology, Shaheen and coworkers describe a mutation in the human WDR4 gene as a cause of primordial dwarfism (PD)." (PMID 26429597, 2015). "A mutation in the WDR4 gene, coding for a tRNA-modifying enzyme, leads to reduced levels of guanosine methylation in tRNA in patients with primordial dwarfism." (PMID 26429597, 2015). "Moreover, mutations in METTL1/WDR4 complex are associated with developmental disorders such as primordial dwarfism and brain malformation." (PMID 37612540, 2023). "Importantly, mutations in human WDR4 impaired tRNA m7G46 methylation and caused microcephalic primordial dwarfism." (PMID 31943105, 2020). "Recent studies have demonstrated that deficiencies in METTL1 or WDR4 abolish tRNA m7G modifications, leading to various pathological conditions, including impaired self-renewal and differentiation of embryonic stem cells, microcephalic primordial dwarfism, and Galloway-Mowat syndrome." (PMID 41292047, 2025). "A variety of WDR4 mutations, including homozygous missense mutations, homozygous splice site mutations, and compound heterozygous mutations have all been identified in patients with neurodevelopmental disorders, including primordial dwarfism and Galloway-Mowat syndrome." (PMID 36681682, 2023).
nasopharyngeal carcinoma (10 papers, 2023 to 2025). A carcinoma arising from the nasopharyngeal epithelium. "Similar to this, elevated METTL1/WDR4 expression in nasopharyngeal carcinoma (NPC) encourages both in vitro and in vivo NPC cell proliferation and metastasis." (PMID 38201505, 2023). "METTL1/WDR4 also promoted nasopharyngeal carcinoma (NPC) cell EMT and chemoresistance to docetaxel and cisplatin by mediating the translation efficiencies of mRNAs in the WNT/β-catenin signaling pathway." (PMID 37612540, 2023). "In addition, the expression of the complex formed by METTL1 and WDR4 was significantly increased in nasopharyngeal carcinoma (NPC)." (PMID 38572667, 2024). "Besides, METTL1/WDR4 is significantly upregulated and correlates with poor prognosis in nasopharyngeal carcinoma (NPC)." (PMID 38943267, 2024). "In nasopharyngeal carcinoma (NPC), METTL1/WDR4 promotes tumorigenesis via regulation of Wnt/β-catenin, and their upregulation has been associated with poor prognosis." (PMID 37369946, 2023). "Elevated expression of METTL1/WDR4 mediates m7G tRNA modification, activates the WNT/β-catenin pathway, and promotes EMT and chemoresistance to cisplatin and docetaxel in nasopharyngeal carcinoma (NPC) cells." (PMID 41194259, 2025).
esophageal squamous cell carcinoma (9 papers, 2022 to 2024). Esophageal squamous cell carcinoma (ESCC) is a type of esophageal carcinoma (EC) that can affect any part of the esophagus, but is usually located in the upper or middle third. "Here we reveal that tRNA m7G methyltransferase complex proteins METTL1 and WDR4 are significantly up-regulated in esophageal squamous cell carcinoma (ESCC) tissues and associated with poor ESCC prognosis." (PMID 35304469, 2022). "METTL1/WDR4 are significantly up-regulated in esophageal squamous cell carcinoma (ESCC), and silencing any of these genes lowers m7G-tRNA modification." (PMID 38201505, 2023). "In esophageal squamous cell carcinoma (ESCC), researchers demonstrated that METTL1 and WDR4 could induce the translation of RPTOR and decrease autophagic flux in ESCC cells." (PMID 38385078, 2024). "The METTL1/WDR4‐mediated m7G modification in tRNA plays a pivotal role in various digestive system neoplasms, including HCC, oesophageal squamous cell carcinoma (ESCC), gastric cancer (GC), intrahepatic cholangiocarcinoma (ICC)." (PMID 38943267, 2024). "Further analysis revealed that METTL1 and WDR4 are upregulated in esophageal adenocarcinoma (EAC) samples and further increased in esophageal squamous cell carcinoma (ESCC) samples." (PMID 35304469, 2022).
intrahepatic cholangiocarcinoma (9 papers, 2022 to 2024). A carcinoma that arises from the intrahepatic bile duct epithelium in any site of the intrahepatic biliary tree. "In intrahepatic cholangiocarcinoma (ICC), there is a significant METTL1/WDR4 upregulation, which is strongly linked to poor prognosis." (PMID 38943267, 2024). "A higher m7G tRNA modification level, as well as the upregulated expression of METTL1 and WDR4, two m7G methyltransferases, were observed in intrahepatic cholangiocarcinoma (ICC) compared to adjacent normal tissues." (PMID 36009465, 2022).
head and neck squamous cell carcinoma (8 papers, 2022 to 2025). A squamous cell carcinoma that arises from any of the following anatomic sites: lip and oral cavity, nasal cavity, paranasal sinuses, pharynx, larynx, and salivary glands. "In addition, the upregulation of the METTL1/WDR4 complex and m7G levels in tRNA were also shown to promote the development and malignancy of head and neck squamous cell carcinoma (HNSCC) by regulating a subset of oncogenic transcripts, including genes related to the PI3K/AKT/mTOR signalling pathway." (PMID 39723662, 2025). "The METTL1/WDR4 complex is abnormally overexpressed in various tumor types, including lung cancer, ESCC, and head and neck squamous cell carcinoma (HNSCC)." (PMID 41446042, 2025).
liver cancer (7 papers, 2022 to 2024). An epithelial or non-epithelial malignant neoplasm that arises from the liver. "In two other studies, the METTL1 / WDR4 mediated modification of tRNA m7G methylation promotes lung and liver cancer progression." (PMID 37528384, 2023). "Up to now, several m7G regulators have been confirmed to promote liver cancer progression by regulating m7G modification of tRNA, such as METTL1and WDR4." (PMID 36339001, 2022). "Among the genes associated with the prognosis of liver cancer, the genes associated with shorter survival period are AGO2, DCPS, IFIT5, LARP1, NCBP2, NUDT10, and NUDT16; the genes associated with longevity are EIF4E3, EIF4G3, METTL1, NCBP1, NSUN2, NUDT11, NUDT4, and WDR4." (PMID 36845384, 2023).
microcephaly (7 papers, 2015 to 2024). A congenital or acquired developmental disorder in which the circumference of the head is smaller than normal for the person's age and sex. "Mutations in WDR4 are associated with primordial dwarfism, characterized by microcephaly and intellectual development challenges, underscoring the critical role of m7G in neurodevelopment." (PMID 39061374, 2024). "Mutations in the WDR4 gene, which are pivotal for m7G modifications, lead to significant neurological disorders, including primary microcephaly and severe growth retardation." (PMID 39061374, 2024). "It has been proposed that mutation in WDR4 causes a unique microcephaly primitive dwarfism by impairing tRNA m7G46 methylation." (PMID 36353111, 2022). "In this regard, the neurological phenotype we observed in patients with WDR4 mutation (severe microcephaly, agenesis of corpus callosum, and lissencephaly) appears to follow the same pattern of bias towards brain involvement." (PMID 26416026, 2015). "Genetic variations of WDR4 have been repeatedly reported in the context of microcephalic disorders such as Galloway-Mowat syndrome 6 (OMIM 618347) and microcephaly, growth deficiency seizures and brain malformations (OMIM 618346)." (PMID 39251572, 2024). "Galloway-Mowat syndrome (GAMOS) is a group of rare hereditary diseases by the combination of early onset steroid-resistant nephrotic syndrome (SRNS) and microcephaly with brain anomalies caused by WDR73, LAGE3, OSGEP, TP53RK, TPRKB, GON7, WDR4 or NUP133 mutations." (PMID 36755238, 2023).
acute myeloid leukemia (6 papers, 2022 to 2026). Acute myeloid leukemia (AML) is a group of neoplasms arising from precursor cells committed to the myeloid cell-line differentiation. "However, the functions and molecular mechanisms of METTL1/WDR4 in acute myeloid leukemia (AML) remain to be determined." (PMID 38268051, 2024). "In acute myeloid leukemia (AML) patients, the Methyltransferase 1/WD repeat domain 4 (METTL1/WDR4) complex catalyzes m7G modification of tRNA, enhancing translation efficiency of specific mRNAs (e.g., HOXA9, MEIS1) to maintain AML cell proliferation and stemness." (PMID 41550494, 2026).
glioma (6 papers, 2022 to 2025). A benign or malignant brain and spinal cord tumor that arises from glial cells (astrocytes, oligodendrocytes, ependymal cells). "We found the WDR4 gene rs15736 was significantly associated with reduced glioma risk (GA/AA vs. GG: adjusted odds ratio = 0.63, 95%confidence interval = 0.42 − 0.94, P = 0.023) out of the eight studied polymorphisms." (PMID 36733406, 2023). "In the present moderate-size case-control study, we found that the WDR4 gene rs15736 was significantly associated with decreased glioma risk." (PMID 36733406, 2023). "Single SNP analyses indicated that only the WDR4 gene rs15736 was significantly associated with glioma susceptibility (GA/AA vs. GG: adjusted OR = 0.63, 95%CI = 0.42 − 0.94, P = 0.023) out of the eight studied SNPs." (PMID 36733406, 2023). "Our finding provided evidence of a causal association between WDR4 gene polymorphisms and glioma susceptibility in Chinese Han children." (PMID 36733406, 2023). "We also found the combined effects of five WDR4 gene polymorphisms on glioma risk." (PMID 36733406, 2023). "Genome-wide annotation of genetic variation by the Human Genome Project enabled us to evaluate the association between the genetic variants in the METTL1 and WDR4 genes and glioma susceptibility in a three-center case-control study (314 cases vs. 380 controls) with Chinese children of Han ethnicity." (PMID 36733406, 2023). "In conclusion, we identified glioma susceptibility loci in the WDR4 gene for Chinese Han Children." (PMID 36733406, 2023). "The findings suggest an association between the WDR4 gene SNPs and pediatric glioma risk." (PMID 36733406, 2023). "In line with this, a comprehensive epitranscriptomic overview in glioma further contextualizes m7G regulators—including METTL1/WDR4 and cap‐dependent readers, within signalling networks and clinical relevance." (PMID 41208200, 2025). "Thus far, only one publication showed the potential implication of m7G methyltransferase complex METTL1/WDR4 in glioma." (PMID 36733406, 2023). "This study is aimed at determining the association of glioma risk with three polymorphisms (rs2291617, rs10877013, and rs10877012) in METTL1 and five polymorphisms (rs2156315 rs2156316, rs6586250, rs15736, and rs2248490) in WDR4 gene in children of Chinese Han." (PMID 36733406, 2023). "For example, METTL1 and WDR4 play a strong carcinogenic role in AML, BC, ESCC, glioma, HCC, HNSCC, ICC, LC, and NPC, promoting the malignant phenotype and progression of tumors; however, METTL1 exerts a significant anti-cancer effect in CC." (PMID 35590385, 2022). "Additionally, a comprehensive epitranscriptomic analysis of glioma further contextualizes m7G regulators, including METTL1/WDR4 and cap‐dependent readers, within key signalling networks, highlighting their clinical relevance in glioma progression." (PMID 41208200, 2025).
bladder cancer (5 papers, 2023 to 2025). "Together, these findings indicate that high expression of WDR4 is associated with the progression and metastasis of bladder cancer, probably in a manner related to the nuclear function of WDR4." (PMID 37783676, 2023). "One of them, WDR4, was associated with poor prognosis and showed much more prominent elevation in bladder cancer tissues than did the other 5 overlapping genes." (PMID 37783676, 2023). "We found that WDR4 was highly expressed in bladder cancer tissues and was associated with prognosis." (PMID 37783676, 2023). "A pancancer study revealed that WDR4 is associated with the prognosis of bladder cancer." (PMID 37783676, 2023). "Compared with that in the control group, WDR4 overexpression promoted the metastasis and proliferation of cancer cells, but simultaneously silencing DDX20 partially reversed the increases in the metastasis and proliferation of bladder cancer cells caused by WDR4 upregulation." (PMID 37783676, 2023). "This study found that WDR4 was highly expressed in bladder cancer and was correlated with metastasis and progression." (PMID 37783676, 2023). "In this study, WDR4 was investigated and found to be highly expressed in bladder cancer tissue by protein profiling." (PMID 37783676, 2023). "As revealed by measurement of luminescence intensity, knockdown of WDR4 significantly suppressed lymphatic metastasis, whereas overexpression of WDR4 markedly accelerated the metastasis of bladder cancer cells to LNs." (PMID 37783676, 2023). "In summary, we found for the first time that WDR4 is highly expressed in the nucleus of cancer cells and promotes LN metastasis and progression in bladder cancer." (PMID 37783676, 2023). "For the first time, we found a nuclear role of WDR4 in a cancer, and we found that WDR4 can affect the progression of bladder cancer through transcriptional regulation." (PMID 37783676, 2023). "Immunohistochemical analysis confirmed that WDR4 expression is also an independent predictor of LN metastasis in bladder cancer." (PMID 37783676, 2023). "Here, we found that elevated expression of WD repeat domain 4 (WDR4) in bladder cancer correlated with worse prognosis." (PMID 37783676, 2023). "Our results reveal a novel mechanism of LN metastasis and progression in bladder cancer and identify WDR4 as a potential therapeutic target for metastatic bladder cancer." (PMID 37783676, 2023). "To investigate how WDR4 regulates bladder cancer progression, we performed co-IP experiments on bladder cancer cells." (PMID 37783676, 2023). "The WDR4 expression level may serve as an independent prognostic factor for LN metastasis in bladder cancer patients." (PMID 37783676, 2023). "We next validated the expression of WDR4 in bladder cancer cells and clinical samples." (PMID 37783676, 2023). "Notably, WDR4 was found to be enriched in the nucleus in bladder cancer cells, and we explored its mechanism and function in the nucleus." (PMID 37783676, 2023). "Furthermore, to assess the predictive value of WDR4 for LN metastasis of bladder cancer, we analyzed clinical information from patients." (PMID 37783676, 2023). "However, we found that the nuclear expression was significantly higher than cytoplasmic expression of WDR4 in bladder cancer cells." (PMID 37783676, 2023). "Together, these results showed that WDR4 promotes LN metastasis in bladder cancer." (PMID 37783676, 2023). "In addition, overexpression of WDR4 increased the migration and invasion abilities of bladder cancer cells." (PMID 37783676, 2023). "How WDR4 is involved in LN metastasis and bladder cancer progression remains a crucial question." (PMID 37783676, 2023). "WDR4 can promote the LN metastasis and proliferation of bladder cancer cells." (PMID 37783676, 2023). "Notably, the expression of WDR4 in the nucleus was significantly higher than that in the cytoplasm in bladder cancer tissue samples, as determined by IHC and IF staining." (PMID 37783676, 2023).
bladder cancer (continued). "We found that WDR4 promotes the metastasis and proliferation of bladder cancer cells." (PMID 37783676, 2023). "Higher WDR4 levels were measured in bladder cancer cells and tissues." (PMID 37783676, 2023). "This suggests that WDR4 may regulate tumor progression through another intranuclear mechanism in bladder cancer." (PMID 37783676, 2023). "Moreover, overexpression of WDR4 obviously increased the proliferation of bladder cancer cells." (PMID 37783676, 2023). "This suggests that WDR4-targeted bladder cancer therapy may be developed in the future." (PMID 37783676, 2023). "Subsequently, we examined whether ARRB2 could reverse the effects of WDR4 in bladder cancer cells." (PMID 37783676, 2023). "However, the role of WDR4 in bladder cancer remains unclear." (PMID 37783676, 2023). "The results revealed that the expression of either WDR4 or DDX20, similar to the correlations with T stage, was an independent predictor of LN metastasis in bladder cancer." (PMID 37783676, 2023). "Thus, WDR4 may interact with DDX20 in the nucleus to promote the progression of bladder cancer." (PMID 37783676, 2023). "To investigate the clinical significance of WDR4 and DDX20, we assembled a cohort of 77 bladder cancer tissues and 30 normal adjacent tissues." (PMID 37783676, 2023). "As an adaptor, WDR4 binds DDX20 and represses the transcription factor Egr1, thereby inhibiting the transcriptional expression of ARRB2 and ultimately promoting the progression of bladder cancer." (PMID 37783676, 2023). "The results of mechanistic studies suggested that WDR4 can recruit DEAD-box helicase 20 (DDX20) into the nucleus and inhibit the transcriptional expression of arrestin beta 2 (ARRB2), thus promoting LN metastasis and progression of bladder cancer." (PMID 37783676, 2023). "WDR4 knockdown inhibited the metastasis and proliferation of cancer cells compared with that of the control cells, and simultaneous silencing of ARRB2 significantly restored the metastasis and proliferation of bladder cancer cells." (PMID 37783676, 2023). "Subsequently, we studied the cooperative role of WDR4 and DDX20 in bladder cancer cells." (PMID 37783676, 2023). "Unlike previous studies of the role of WDR4 in the tumor cell cytoplasm, our study unexpectedly showed a significant increase in the nuclear expression of WDR4 as malignancy increased in bladder cancer." (PMID 37783676, 2023). "In our mass spectrometry analysis, the level of WDR5 in bladder cancer tissues was also found to be increased, but this increase was not as great as the fold increase in the WDR4 level." (PMID 37783676, 2023). "In addition, bladder cancer tissues of patients with LN metastasis displayed markedly higher WDR4 and DDX20 levels than those without LN metastasis." (PMID 37783676, 2023).